CDK4 (cyclin dependent kinase 4)
Diseases named in the same sentence as CDK4 in open-access papers (continued):
Sharing a sentence is not in itself a finding about the gene and the disease.
breast cancer (continued). "Trials concerned with all of these aspects are currently underway, and hopefully they will further illuminate the true value of CDK4/6 inhibition in breast cancer therapy." (PMID 34830174, 2021). "In advanced luminal breast cancer, CDK4/6 inhibitors demonstrated a remarkable improvement in PFS and OS, and recently, the biomarkers PIK3CA and BRCA have defined a new strategy of treatment." (PMID 34680350, 2021). "Inhibitors targeting CDK4/6 activation (CDK4/6i) have made important progresses in breast cancer treatment." (PMID 33809714, 2021). "The role of cyclin E in mediating resistance to CDK4/6 inhibition has been extensively documented in ER+ breast cancer cells." (PMID 33599863, 2021). "Three CDK4/6 inhibitors are approved for the treatment of oestrogen receptor-positive (ER+) breast cancer and our results support further preclinical examination of a CDK4/6 inhibitor in combination with lapatinib or tucatinib." (PMID 33473169, 2021). "Cyclin-dependent kinase 4 and 6 (CDK4/6) inhibitors are widely used for the treatment of advanced estrogen receptor (ER)-positive breast cancer." (PMID 34244855, 2021). "In the last years, different CDK4/6 inhibitors have been approved for the treatment of breast cancer and have been tested in late-phase trials in other malignancies." (PMID 34440249, 2021). "Further, we found that high levels of phospho-AKT (p-AKT) in metastatic lesions from ER+ breast cancer patients treated with combined endocrine therapy and CDK4/6i in the advanced setting correlated with shorter PFS." (PMID 34433817, 2021). "In fact, CDK4/6 specific small molecule inhibitors already have been approved by the FDA for use in treating breast cancer." (PMID 34930213, 2021). "Next, we investigated the clinical relevance of higher levels of p-AKT in MCF-7 and ZR-75-1 breast cancer cells resistant to fulvestrant and combined fulvestrant and CDK4/6i (MPF-R cells)." (PMID 34433817, 2021). "This suggests that breast cancer resistant to CDK4/6 inhibitors retains sensitivity to chemotherapeutic agents." (PMID 32860163, 2021). "For instance, knockdown of CDK4 in the mouse model of NSCLC results in the CDK6-induced expression of mutant K-Ras and CDK4/6 inhibitor treatment in breast cancer cells results in the amplification of CDK6 through a feedback mechanism." (PMID 34771669, 2021). "Selective CDK4/6 inhibitors such as palbociclib, ribociclib, and abemaciclib have achieved curative effects in breast cancer." (PMID 34434893, 2021). "In a novel syngeneic preclinical model of ER + mammary carcinoma efficacy of radiotherapy combined with CDK4/6 inhibitor palbociclib and tamoxifen were investigated in various doses and therapeutic schedules." (PMID 34078406, 2021). "Accordingly, the combination of mTORC1 and CDK4/6 inhibitors reduces cancer cell growth more effectively and delays resistance to therapy in models of breast carcinoma, anaplastic thyroid carcinoma, and cholangiocarcinoma." (PMID 34360912, 2021). "Nar isolated from Thymus vulgaris upregulated pro-apoptotic markers, p18, p19, p21, Bax and Bak, and downregulated anti-apoptotic markers, Cdk4, Cdk6, Cdk7, and Bcl-2 in human colorectal and breast cancer cells leading to apoptosis." (PMID 33192517, 2020). "The ensemble of these observations strongly supported the development of CDK4/6 inhibitors in breast cancer treatment." (PMID 32210163, 2020). "Recently reported that knockdown FZR1 and Rb in human breast cancer cells promote cell division arrest by CDK4/6-specific inhibitor Palbociclib (PD0332991) treatment." (PMID 32978372, 2020). "As CDK4/6 inhibitors are approved for the clinical treatment of breast cancer, the MCF7 cell line was treated with LY2835219 and metformin for confirmation." (PMID 33116117, 2020). "Based on our findings, we proposed that the inhibition of CDK4/6 activity blocks breast cancer EMT and metastasis by decreasing the protein stability of ZEB1." (PMID 32296027, 2020).
breast cancer (continued). "The successful application of CDK4/6 inhibitors in HR+/HER2− breast cancers brings great clinical benefits to patients and gives more encouragement to physicians and researchers." (PMID 32357912, 2020). "CDK4/6i have been tested for treating a list of solid tumor types, with particular success for certain breast cancer." (PMID 32843618, 2020). "It was shown that besides p38, MKK3 can bind to multiple other proteins, including several drivers of breast cancer, such as CDK4, AURKA, FGFR4, EPHA2, and MYC." (PMID 32873298, 2020). "Currently, inhibition of CDK4/6 in combination with endocrine therapies is the treatment option in hormone receptor-positive/HER2-negative advanced breast cancer." (PMID 32197329, 2020). "Gain of the CCND1 and CDK4 and loss of the CDKN2A (p16) and CDKN2C (p18) genes are present in patients with luminal B breast cancer and poor prognosis of and negatively regulated by the cell cycle pathway." (PMID 33110086, 2020). "We show that targeting PI3K alone or in combination with inhibitors of CDK4/6 and endocrine therapies can overcome acquired resistance and potentially prevent the emergence of resistance to CDK4/6-ER-based therapies for ER+/HER2− breast cancer." (PMID 32795346, 2020). "Resistance to CDK4/6i plus ET represents the next clinical challenge for the breast cancer community to overcome and requires a deep understanding of the mechanism of CDK4/6i resistance in an endocrine sensitive and resistant setting." (PMID 33353132, 2020). "Despite the wide use of CDK4/6 inhibitors in the treatment of breast cancer, published data regarding possible contraindications and interactions with radiation treatment are still very limited." (PMID 32788596, 2020). "Cyclin D1 deficiency has been shown to impair mammary epithelial proliferation while cyclin D1 and CDK4 are necessary for breast cancer development in mice and cyclin D1 is overexpressed in the majority of human breast cancers." (PMID 32012988, 2020). "Considering the wide use of CDK4/6 inhibitors in HR-positive breast cancer, our resistant model will be very valuable to develop drugs to overcome resistance." (PMID 33260316, 2020). "Several studies investigating mechanisms of resistance in breast cancer patients treated with PI3K inhibitors or CDK4/6 inhibitors have found interesting results regarding the implication of PTEN in the development of resistance." (PMID 32605290, 2020). "A high expression of Cyclin D1 and CDK4 is frequently found in breast cancer and deregulation of this pathway contributes to uncontrolled proliferation in hormone receptor-positive breast cancer." (PMID 33255177, 2020). "In those reports, miR-124 targeted SphK1 and Cdk4 in squamous carcinoma and breast cancer cells, respectively." (PMID 32963317, 2020). "Preclinical studies have supported the use of CDK4/6 inhibitors in the treatment of HER2-positive breast cancers, this strategy being particularly promising in HER2+ER+ tumors for the presence of a crosstalk between signaling-linked to HER2 and ER." (PMID 32210163, 2020). "We performed a retrospective preliminary analysis of breast cancer patients treated at our Center with palliative radiation therapy and concurrent CDK4/6 inhibitors." (PMID 32788596, 2020). "Mitogenic action of estrogen in ER-dependent breast cancers is mediated via the induction of Cyclin D1 that can then bind to CDK4 and CDK6 resulting in the hyperphosphorylation of the retinoblastoma (Rb) tumor suppressor protein." (PMID 32795346, 2020). "Nevertheless, the effect of CDK4/6 inhibition extends to breast cancer patients with acquired resistance to endocrine therapy." (PMID 33255177, 2020). "Recently, several clinical trials have demonstrated that the addition of CDK4/6 selective inhibitors to endocrine therapy has improved progression-free survival as well as overall survival in patients with advanced breast cancer." (PMID 32650578, 2020).
breast cancer (continued). "Ribociclib (RBC, Kisqali®) is a highly selective CDK4/6 inhibitor that has been approved for breast cancer therapy." (PMID 35514564, 2020). "Combination of CDK4/6 inhibitors and endocrine therapy improves clinical outcome in advanced oestrogen receptor (ER)-positive breast cancer, however relapse is inevitable." (PMID 32307447, 2020). "As high expression levels of Cyclin D1 and CDK4 are frequently found in breast cancer and contribute to uncontrolled proliferation, they are potential candidates for biomarkers." (PMID 33255177, 2020). "The co‐treatment with CDK4/CDK6 and AKT inhibitors demonstrated the inhibition of RB‐positive, but RB‐deficient, breast cancer cells." (PMID 32508030, 2020). "Clinical trials have confirmed that CDK4/6 inhibitors alone or combined with endocrine therapy have brought great clinical benefit to HR+/HER2− breast cancer patients." (PMID 32357912, 2020). "The three CDK4/6 inhibitors are used in estrogen receptor (ER)-positive breast cancer based on clinical trials demonstrating improved progression-free survival when combined with antiestrogen therapy, the golden standard for treatment of ER-positive disease." (PMID 32260549, 2020). "Cyclin-dependent kinase 4 and 6 (CDK4/6) inhibitors have shown significant efficacy in ER+ breast cancer." (PMID 32393270, 2020). "The role of miR-29b-5p and CDK4 on the palbociclib insensitivity in breast cancer should also be investigated in the future." (PMID 32934206, 2020). "Ribociclib is an orally available cyclin-dependent kinase 4 and 6 (CDK4/6) inhibitor that is approved for the treatment of breast cancer." (PMID 32626773, 2020). "TROJAN promotes ER+ breast cancer proliferation and is a potential target for reversing CDK4/6 inhibitor resistance." (PMID 32393270, 2020). "In the present study, we provide evidence that the specific inhibition of CDK4/6 results in a significant decrease in ZEB1 protein stability that subsequently blocks tumor metastasis in breast cancer both in vitro and in vivo." (PMID 32296027, 2020). "Previous study showed high expression of cyclins D1 in HER2 overexpressing breast cancer and pyrotinib treatment potently decrease the protein level of Cyclin D1 and CDK4 in HER2 positive human breast cancer cell lines." (PMID 32022229, 2020). "At the time of writing, we identified 12 ongoing trials of CDK4/6 inhibitors combined with hormonal agents in ER+ breast cancer patients that were candidates for NET." (PMID 32429381, 2020). "Else, in breast cancer models, cells activate autophagy in response to Palbociclib, and blockade of autophagy significantly improved the efficacy of CDK4/6 inhibition in in vitro and in vivo breast cancers models with an intact G1/S transition." (PMID 33105796, 2020). "CDK4/6 inhibitors have greatly changed the treatment landscape of HR-positive breast cancer patients, stimulating further explorations of combination therapy." (PMID 32933570, 2020). "The development of CDK4/6 inhibitors has been a significant advancement in luminal breast cancer therapy." (PMID 33364954, 2020). "In the present study, we generated in vitro and in vivo models of ER+/HER2− breast cancer with acquired resistance to both CDK4/6 inhibitor monotherapy and combination therapy with hormone blockade." (PMID 32795346, 2020). "UALCAN cancer database analysis indicated that the expression of cdk4 and e2f1 in breast cancer was significantly higher than that in normal tissues (p < 0.01), while the expression of cdk6 and rb1 was not higher than that in normal tissues." (PMID 32357912, 2020). "First, long-term exposure to CDK4/6 inhibitors induces the cellular senescence phenotype in many cancer cell lines, such as breast cancer, neuroblastoma, and melanoma." (PMID 32933570, 2020). "In summary, we demonstrated an alternative mechanism for the CDK4/6-USP51 axis in regulating breast cancer metastasis that supplements the deubiquitination and stabilization of ZEB1." (PMID 32296027, 2020).
breast cancer (continued). "We therefore performed a retrospective preliminary analysis of breast cancer patients treated at our Center with palliative radiation therapy to bone lesions and concurrent CDK4/6 inhibitors to assess the possible pitfalls of this combination." (PMID 32788596, 2020). "CDKs have long been considered promising therapeutic targets in a variety of pathologies, and the recent therapeutic success of CDK4/6 inhibitors in breast cancers has renewed interest in their therapeutic potential." (PMID 32175313, 2020). "Pioneering X-ray crystallography work lead to the discovery that this mechanism of action is mimicked by the CDK4/6 inhibitor Palbociclib, which is successfully used in the clinic for certain breast cancers." (PMID 33166394, 2020). "Nowadays, CDK4/6 inhibitors are mainly applied on breast cancer therapy and there are few selective CDK4/6 inhibitors for HCC treatment." (PMID 33009370, 2020). "Although main battlefield in HR+/HER2− breast cancer, CDK4/6 inhibitors have also been actively explored in other malignancies." (PMID 32357912, 2020). "Despite these limitations, our findings provide a rationale for clinical application of PARPi in the setting of combination with CDK4/6i to treat breast cancer." (PMID 32249776, 2020). "Preclinical work in our laboratory first demonstrated that hormone receptor-positive breast cancer cell lines are differentially sensitive to the CDK4/6 inhibitor palbociclib when compared to other breast cancer subgroups." (PMID 32795346, 2020). "The SY-1365 trial was designed to target specific cohorts of patients with resistance to prior treatments, including platinum resistance in ovarian cancer and CDK4/6 inhibitor plus aromatase inhibitor resistance in HR+ breast cancer." (PMID 32385714, 2020). "Since CDK inhibitors were developed 20 years ago, CDK4/6 inhibitors have achieved great success in breast cancer, and cell cycle therapy has gradually matured." (PMID 32357912, 2020). "We investigated mechanisms of resistance to CDK4/6 inhibitor in breast cancer and potential therapeutic strategies." (PMID 33260316, 2020). "As a new-generation CDK inhibitor, a CDK4/6 inhibitor combined with endocrine therapy has been successful in the treatment of advanced estrogen receptor–positive (ER+) breast cancer." (PMID 33364954, 2020). "Although selective CDK4/6 inhibition results in less toxicity, a huge challenge is that breast cancer (including basal-like breast cancer) adapt quickly to CDK4/6 inhibition, while inhibiting CDK2 simultaneously is an effective solution." (PMID 33246450, 2020). "As medical science has advanced, three selective CDK4/6 inhibitors (palbociclib, ribociclib, and abemaciclib) have achieved fairly good curative benefits in breast cancer." (PMID 32357912, 2020). "While rare, we noticed clinically significant mutations in CDKN2A, which belongs to the cell cycle pathway, in the HER2+ subtype of breast cancer (P < 0.05), indicating the potential benefit of CDK4/6 inhibitors." (PMID 33173047, 2020). "Despite its relative rarity in breast cancer, this population is important as MMR-deficient cancers have been highly responsive to immune therapies such as PD-1 or CDK4/6 checkpoint inhibitors." (PMID 31522348, 2020). "While it is reasonable to consider using CDK4/6i beyond breast cancer, it turns out to be challenging because of (i) unsatisfactory efficacy, (ii) drug resistance, (iii) lack of reliable biomarkers for patient selection, and (iv) toxicity." (PMID 32843618, 2020). "Currently, inhibitors targeting CDK4/6 have been clinically approved for breast cancer patients who have failed hormone receptor-targeted treatment." (PMID 33110086, 2020). "In this study, we used in vitro and in vivo breast cancer models of acquired resistance to CDK4/6-based therapies to characterize molecular mechanisms associated with therapeutic resistance." (PMID 32795346, 2020).
breast cancer (continued). "The investigations provided proof that using CDK4/6 inhibitors have shown the value of cancer therapy by governing the proliferation of breast cancer." (PMID 33014527, 2020). "Of further notice, the use of neoadjuvant CDK4/6 inhibitors combined with AI in ER+ HER2+ breast cancer patients, who represent the elective population target for the phase II trial NCT02907918." (PMID 32429381, 2020). "This was because the FDA has approved a CDK4/6i (palbociclib) for the treatment of breast cancer, in which PARPis have also shown promising clinical activity." (PMID 32249776, 2020). "A number of CDK4/6 inhibitors are clinically approved for use in combination with endocrine therapies for the treatment of ER+ breast cancer, however, resistance to these drugs is an emerging problem." (PMID 32385714, 2020). "It was previously reported that CDK4/6 inhibitors activated the PI3K/AKT pathway through the phosphorylation of S473/T308 on AKT and CDK4/6 and PI3K inhibitor combination reduced AKT phosphorylation in PIK3CA mutated breast cancer cell lines." (PMID 32899250, 2020). "Currently many CDK inhibitors are in clinical use, including the CDK4/6 inhibitor palbociclib, which showed a synergistic effect with endocrine therapy in patients with ERα+ breast cancer." (PMID 32340192, 2020). "In contrast, the potent cyclin dependent kinase inhibitor p21 which binds to and inhibits the activity of cyclin-CDK2, -CDK1, and -CDK4/6 complexes, was dose-dependently upregulated in both breast cancer cell lines and to a lesser extend in MCF-10A." (PMID 32292575, 2020). "Results from clinical trials suggest that the E2F transcriptional pathway is an important factor for treatment with CDK4/6 inhibitors in breast cancer." (PMID 32650578, 2020). "In ER+ breast cancer, the CDK4/6-CCND1-RB1 axis is a critical pathway in tumor cell cycle regulation." (PMID 32393270, 2020). "In other breast cancer subtypes, such as triple negative breast cancer, clinical trials of CDK4/6 inhibitors in combination with anti-androgen inhibitors are still ongoing." (PMID 33364954, 2020). "Increased expression of cyclin D causes continuous phosphorylation of Rb and leads to continuous proliferation of breast cancer cells; blocking CDK4/6 exerts a lethal effect on breast cancer cells." (PMID 32357912, 2020). "CDK4/6 inhibitors in combination with endocrine therapy are the standard of care for advanced breast cancer in the first- and second-line treatment settings." (PMID 32787886, 2020). "Recently, the addition of the CDK4/6 inhibitors, such as palbociclib (PD; also known as PD 0332991), significantly improved the progression-free survival of advanced ER+ breast cancer patients." (PMID 32393270, 2020). "Preclinical studies showed also that combined inhibition of CDK4/6, mTORC 1–2, and ER induces marked and durable regression of ER+ breast cancer models." (PMID 32210163, 2020). "In the clinical treatment of advanced breast cancer, CDK4/6 inhibitors are applied to prevent disease progression." (PMID 33282725, 2020). "In the present study, we reported that the inhibition of CDK4/6 significantly reduced breast cancer EMT and metastasis through the induction of ZEB1 protein degradation." (PMID 32296027, 2020). "Intriguingly, the expression of cdk4, cdk6, e2f1, and rb1 in breast cancer was moderate or low compared to that in all tumors." (PMID 32357912, 2020). "The randomized phase II PALLET trial investigated the addition of palbociclib, a CDK4/6 inhibitor, to neoadjuvant letrozole in postmenopausal women with ER+ breast cancer." (PMID 32690069, 2020). "Our finding extends the concept of combined blockade of the CDK4/6 and c-myc signaling pathways to increase palbociclib sensitivity, making c-myc a promising biomarker for palbociclib sensitivity in breast cancer." (PMID 32934206, 2020).